IREB2 (iron responsive element binding protein 2)
Diseases named in the same sentence as IREB2 in open-access papers (continued):
Sharing a sentence is not in itself a finding about the gene and the disease.
cancer (38 papers, 2010 to 2025). A tumor composed of atypical neoplastic, often pleomorphic cells that invade other tissues. "Therefore, ACO1 and IREB2 can work as independent risk factors and prognostic biomarkers of several types of cancer." (PMID 36059676, 2022). "In current research, the phenomenon that ACO1 and IREB2 are involved in numerous cascades were revealed in GO along with the KEGG pathway enrichment analyses of ACO1, IREB2 and the linked genes, especially the PD-L1 expression state and PD-1 checkpoint cascade in cancer." (PMID 36059676, 2022). "Cancer‐associated genes (VIM, IGHG1‐4, IGKC, IGHA1) were upregulated, and CPCAT data revealed correlations of IREB2 with IGHG1 and VIM, and CD27 with IGHG1." (PMID 41377765, 2025). "Iron load leads to cell proliferation in cancer cell lines, and cancer cell lines have a poor ability to regulate IREB2 expression." (PMID 34938740, 2021). "The suppression of IREB2 (iron responsive element binding protein 2), a transcription factor, limits ferroptotic cancer cell death by regulating iron metabolism." (PMID 32103754, 2020). "Further studies are needed to prove the link between IREB2 protein and cancer biology." (PMID 26310313, 2015). "Therefore, the misexpression of IREB2 gene may alter intracellular iron levels and hence lead to the occurrence of malignant tumors." (PMID 34938740, 2021). "Finally, the iron-responsive element binding protein 2 (IRP2) that promotes the transcription of transferrin and the family of iron–sulfur (Fe-SA) cluster biogenesis proteins have also been described to be succinated when fumarate accumulates in cancer cells." (PMID 31900386, 2020). "In the diversity of cancers, the ACO1 locus on chromosome 9p21.1 and IREB2 locus on chromosome 15q25.1 are generally deleted." (PMID 36059676, 2022). "Considering the expression level of ACO1 and IREB2 were closely related to progression and metastasis in KIRC patients, we then assessed their value in cancer prognosis." (PMID 36059676, 2022). "Dysregulation of IREB2 expression or function can result in imbalances in iron metabolism, contributing to oxidative stress and inflammation—key mechanisms in COPD pathogenesis and other diseases, such as neurodegenerative disorders and cancer." (PMID 41007821, 2025). "IREB2, as an iron sensor, participates in the regulation of iron transport proteins and promotes iron uptake and ferroptosis in cancer cells, which significantly increases the release of HMGB1 in the tumor stroma and promotes the CD8+ T cells infiltration in cancer." (PMID 38288118, 2023). "Moreover, lipocalin 2 (LCN2) inhibits ferroptosis by limiting iron uptake, while aconitase 1 (ACO1, also known as IRP1) and iron responsive element binding protein 2 (IREB2, also known as IRP2) promote ferroptosis in cancer cells by regulating the translation of iron metabolism-related protein." (PMID 34742351, 2021). "Although paralogous synthetic lethal pairs like STAG1/STAG2 and IREB2/ACO1 are interesting biologically, how the large therapeutic window of these paralogous synthetic lethal interactions can be translated into potential cancer therapeutics is an open question." (PMID 34462321, 2021). "In contrast to COPD, the potential role of the IREB2 gene in human cancer is not well documented." (PMID 26310313, 2015).
infection (17 papers, 2009 to 2025). The state of being infected such as from the introduction of a foreign agent such as serum, vaccine, antigenic substance or organism. "The IREB2, MUT, ALDH1A2, and ALDH1B1 genes formed another cluster, with MUT, ALDH1A2, and ALDH1B1 showing associations with cardiovascular disease or infection." (PMID 39194753, 2024).
neurodegenerative disease (9 papers, 2011 to 2026). A disorder of the central nervous system characterized by gradual and progressive loss of neural tissue and neurologic function. "IREB2 knock-out mouse models have a predisposition to developing neurodegenerative disease due to aberrant cellular iron homeostasis, though the lungs of these animals were not examined in any detail." (PMID 21320324, 2011). "Excess iron can be toxic, but the mechanism of neurodegenerative disease is unclear; work is in progress to further characterize the functional pathways impacted by IREB2 in the lung." (PMID 22356581, 2012). "IREB2-/- mice have aberrant iron homeostasis and accumulate iron in the intestine and the central nervous system(CNS); the CNS accumulation may lead to neurodegenerative disease." (PMID 22356581, 2012).
neurological disorder (6 papers, 2018 to 2025). "Recently, two patients with mutations in IREB2 have been identified that exhibit early onset and progressive neurological disease, and microcytic anemia; however, insulin sensitivity and secretion were not reported for these patients." (PMID 31941883, 2020).
movement disorder (2 papers, 2024 to 2026). Neurological conditions resulting in abnormal voluntary or involuntary movement, which may impact the speed, fluency, quality and ease of movement. "Homozygous knock-out of Ireb2 in a mouse model leads to iron metabolism dysregulation and a progressive movement disorder." (PMID 40836029, 2026).
liver (1 paper, 2022). "Consequently, we hypothesized that IREB2 plays an important role in ferroptosis of steatotic liver IRI and SHP-HR." (PMID 35720183, 2022).
neurodevelopmental disorder (1 paper, 2026). A behavioral and cognitive disorder with onset during the developmental period that involves impaired or aberrant development of intellectual, motor, or social functions. "Replication in a person who stutters is required to confirm that stuttering is a feature of the monogenic neurodevelopmental disorders associated with mutations in SPTBN1, PRPF8, TRIO, and ZBTB7A, and to causally link FLT3 and IREB2 to neurodevelopmental disorders." (PMID 40836029, 2026). "Genes of interest FLT3 and IREB2 have not been associated with a neurodevelopmental disorder." (PMID 40836029, 2026).
IREB2 also shares sentences with these, for which no sentence is quoted: anemia (11 papers); diabetes (5); neuroblastoma (4); polycythemia (4); prostate carcinoma (4); Sepsis (4); breast tumor (3); erythropoietic protoporphyria (3); hereditary hemochromatosis (3); insulinoma (3); iron overload (3); pulmonary hypertension (3); urinary tract infection (3); bacteremia (2); chronic bronchitis (2); colibacillosis (2); Endometrial Cyst (2); genetic disorder (2); Glucose intolerance (2); leukemia (2); liver cancer (2); neutropenia (2); periodontitis (2); plague (2); renal cell carcinoma (2); respiratory infection (2); Respiratory tract infection (2); viral infection (2); Age-related cataract (1); Anxiety (1).
A further 69 diseases each share a sentence with IREB2 in 1 paper.